GOT1 (glutamic-oxaloacetic transaminase 1)
Description:
Biosynthesis of L-glutamate from L-aspartate or L-cysteine. Important regulator of levels of glutamate, the major excitatory neurotransmitter of the vertebrate central nervous system. Acts as a scavenger of glutamate in brain neuroprotection. The aspartate aminotransferase activity is involved in hepatic glucose synthesis during development and in adipocyte glyceroneogenesis. Using L-cysteine as substrate, regulates levels of mercaptopyruvate, an important source of hydrogen sulfide. Mercaptopyruvate is converted into H(2)S via the action of 3-mercaptopyruvate sulfurtransferase (3MST). Hydrogen sulfide is an important synaptic modulator and neuroprotectant in the brain. In addition, catalyzes (2S)-2-aminobutanoate, a by-product in the cysteine biosynthesis pathway.
Synonyms: cAspAT; cCAT; AST1; SGOT; AST; ASTQTL1; GIG18
Tractability: Small molecule: a structure with a bound ligand is known. PROTAC: ubiquitination databases record sites on it; its protein half-life has been measured; a small molecule that binds it is known.
Target class: Enzyme; Transferase
Gene: Protein-coding gene on chromosome 10 (99,396,870 to 99,430,671, reverse strand). Ensembl gene ENSG00000120053.
Subcellular location: Cytoplasm
Pathways (Reactome):
Metabolism: Aspartate and asparagine metabolism; Malate-aspartate shuttle; Methionine salvage pathway
Gene Ontology:
Molecular function: 2-aminobutanoate transaminase activity; L-aspartate:2-oxoglutarate aminotransferase activity; protein binding; L-cysteine transaminase activity; carboxylic acid binding; catalytic activity; phosphatidylserine decarboxylase activity; pyridoxal phosphate binding; transaminase activity
Biological process: cellular response to insulin stimulus; L-aspartate catabolic process; malate-aspartate shuttle; response to glucocorticoid; 2-oxoglutarate metabolic process; aspartate biosynthetic process; aspartate metabolic process; glutamate metabolic process; glycerol biosynthetic process; amino acid metabolic process; cellular response to cAMP; cellular response to glucagon stimulus; cellular response to mechanical stimulus; dicarboxylic acid metabolic process; gluconeogenesis; L-glutamate biosynthetic process; negative regulation of collagen biosynthetic process; negative regulation of cytosolic calcium ion concentration; negative regulation of mitochondrial depolarization; oxaloacetate metabolic process; positive regulation of transforming growth factor beta receptor signaling pathway; response to cadmium ion; response to carbohydrate; response to immobilization stress; response to transition metal nanoparticle; and 1 more
Cellular component: cytoplasm; extracellular exosome; nucleus; cytosol; axon terminus
Genetic constraint (gnomAD): Loss-of-function variants: 19 observed, 40.41 expected, observed/expected ratio (o/e) 0.47, 90% interval 0.33 to 0.69. The upper end of that interval is the gene's LOEUF score, 0.69, which puts it in group 2 of 6, group 1 being the genes least tolerant of losing a copy. Missense variants: 326 observed, 480.98 expected, observed/expected ratio (o/e) 0.68, 90% interval 0.62 to 0.74. Synonymous variants: 168 observed, 184.76 expected, observed/expected ratio (o/e) 0.91, 90% interval 0.8 to 1.03.
Homologues: Orthologues: chimpanzee GOT1 (100% identical), macaque GOT1 (98% identical), pig GOT1 (93% identical), dog GOT1 (92% identical), guinea pig GOT1 (92% identical), mouse Got1 (91% identical), rat Got1 (90% identical), tropical clawed frog got1 (81% identical), zebrafish got1 (76% identical), rabbit GOT1 (75% identical), Drosophila melanogaster Got1 (56% identical), Caenorhabditis elegans got-1.2 (54% identical). Paralogues in human: GOT2 (49% identical), GOT1L1 (40% identical).
Diseases named in the same sentence as GOT1 in open-access papers:
GOT1 is named in the same sentence as 199 diseases in open-access papers, as found by Europe PMC text mining. Sharing a sentence is not in itself a finding about the gene and the disease. The quoted sentences say what the papers report.
pancreatic cancer (47 papers, 2014 to 2026). "Circ-MBOAT2 acted as a sponge of miR-433-3p, which was associated with GOT1 and repressed cell proliferation, migration, invasion, and glutamine catabolism in pancreatic cancer." (PMID 38612727, 2024). "GOT1 is closely associated with cancer, and its high expression can promote the development of tumors such as pancreatic cancer, colorectal cancer, and breast cancer, or as a potential biomarker such as a diagnostic marker for prostate cancer or a prognostic marker for acute myeloid leukemia." (PMID 41327788, 2025). "Considering the importance of GOT1 in regulating glutamine catabolism, we hypothesized that GOT1-mediated pancreatic cancer progression was linked to NRF2." (PMID 33832516, 2021). "The research also explored the potential of GOT1 inhibition as a novel therapeutic strategy for pancreatic cancer." (PMID 40733146, 2025). "For instance, inhibiting GOT1 was shown to induce ferroptosis-mediated death in pancreatic cancer cells." (PMID 40390008, 2025). "In pancreatic cancer, in response to chronic acidosis stress, the expression of GOT1 was increased in cancer cells to fuel oxidative metabolism by enhancing the non-canonical Gln metabolism." (PMID 39777342, 2024). "In the initial stage of our research, the GSE157830 dataset, containing expression profiles related to GOT1 knocked‐down human pancreatic cancer cell lines Tu8902 and MiaPaCa, was downloaded from the GEO database, and DEGs were analysed." (PMID 38682349, 2024). "Conversely, glutamic-oxaloacetic transaminase 1 (GOT1) inhibits ferritinophagy-mediated ferroptosis in pancreatic cancer cells." (PMID 38844964, 2024). "The aspartate aminotransaminase (GOT1) is a famous ferroptosis suppressor gene in pancreatic cancer." (PMID 38682349, 2024). "The expression of GOT1 was also up-regulated in pancreatic cancer cell-derived exosomes, promoting cancer cell proliferation, migration, and invasion." (PMID 39777342, 2024). "GOT1 has been shown to be essential for redox balance and survival in pancreatic cancer cells through the generation of NADPH." (PMID 38725581, 2023). "GOT1 has been shown to be critical for maintaining mitochondrial oxidative phosphorylation as well as redox balance in pancreatic cancer cells through the production of NADPH, and ME1 is required for the generation of NADPH in this pathway." (PMID 38725581, 2023). "Inhibition of cytosolic aspartate aminotransaminase (GOT1) enhances pancreatic cancer cell death via ferroptosis." (PMID 36942991, 2023). "GOT1-mediated pathways play vital roles in maintaining redox homeostasis in pancreatic cancer, and increased enzymatic activity of GOT1 favors the growth of cancer cells." (PMID 36959802, 2023). "Next, we examined the collected tumor tissues and adjacent tissues from 30 pancreatic cancer patients and found that GOT1 expression was significantly elevated in tumor tissues compared with adjacent tissues." (PMID 36497150, 2022). "For example, inhibition of glutamate oxaloacetate transaminase 1 (GOT1) in pancreatic cancer cells induced energetic stress, marked by the induction of autophagy and ferritinophagy." (PMID 35065965, 2022). "It was studied that knockdown of GOT1 results in escalation of ROS levels and inhibition of cell growth in pancreatic cancer cells, indicating GOT1 as a prognostic marker for pancreatic cancer." (PMID 36499136, 2022). "There is already evidence that inhibition of GOT1 promotes pancreatic cancer cell death via ferroptosis." (PMID 36430911, 2022). "We found abnormally high expression of GOT1 in pancreatic cancer progression by bioinformatics database analysis." (PMID 36497150, 2022). "A previous study demonstrated that the knockdown of GOT1 impairs the viability of pancreatic cancer cells." (PMID 36499136, 2022). "In this study, we found that GOT1 protein enriched in exosomes secreted by pancreatic cancer cells promoted tumor cell proliferation, invasion and migration and inhibited cell iron death." (PMID 36497150, 2022).
pancreatic cancer (continued). "The results of online bioinformatics database analysis indicated that CCR2 was a potential binding protein of GOT1 and is highly expressed in pancreatic cancer tissues." (PMID 36497150, 2022). "Currently, studies have confirmed that GOT1 inhibition promotes pancreatic cancer cell death by triggering ferroptosis." (PMID 36497150, 2022). "Summarily, these findings demonstrated miR-433-3p regulated pancreatic cancer progression and glutamine metabolism by targeting GOT1." (PMID 33832516, 2021). "Here, we sought to identify metabolic dependencies following GOT1 inhibition to exploit this feature of pancreatic cancer and to provide additional insight into regulation of redox metabolism." (PMID 34381026, 2021). "Here, the authors show that inhibition of GOT1 in pancreatic cancer cells leads to cell death via ferroptosis." (PMID 34381026, 2021). "The significantly high expression of GOT1 in pancreatic cancer tissues also was found in UALCAN dataset." (PMID 33832516, 2021). "Subsequently, data also displayed the mRNA and protein expression of GOT1 were greatly increased in pancreatic cancer tissues as well as PANC-1 and SW1990 cells compared with paracancerous normal tissues and HPDE cells, respectively." (PMID 33832516, 2021). "Next, we studied the effects of GOT1 overexpression on GOT1 knockdown-mediated pancreatic cancer cell processes." (PMID 33832516, 2021). "Circ-MBOAT2 modulated tumor development and glutamine catabolism by miR-433-3p/GOT1 axis in pancreatic cancer." (PMID 33832516, 2021). "Circ-MBOAT2 and GOT1 expression were significantly upregulated, while miR-433-3p expression was downregulated in pancreatic cancer tissues and cells compared with normal pancreatic tissues or cells." (PMID 33832516, 2021). "Recently, it has been reported that the limiting of exogenous cystine can promote the ferroptosis of pancreatic cancer cells by enhancing the transaminase enzyme GOT1 inhibition." (PMID 34796174, 2021). "Inhibition of GOT1 had been validated to be an effective strategy to impair cancer growth in pancreatic cancer and lung cancer." (PMID 33276753, 2020). "Consistently, pancreatic cancer cells upregulate the expression of GOT1 in the acidic microenvironment to deal with increased ROS generation and support cancer cell survival." (PMID 32122374, 2020). "Our work suggested that AO, a selective GOT1 inhibitor, has potential to be a novel agent for pancreatic cancer therapy." (PMID 31470862, 2019). "Then we demonstrated that AO can selectively inhibit pancreatic cancer cell proliferation, and downregulation of GOT1 in pancreatic cancer cells significantly enhanced AO-induced growth-inhibitory effects." (PMID 31470862, 2019). "Notably, microRNAs such as miR-2115-3p and miR-9-5p have been reported to bind to Got1 mRNA and suppress its expression in trophoblast cells and pancreatic cancer cells, respectively." (PMID 40741328, 2025). "Combining GOT1 inhibitors with other anticancer agents may enhance its therapeutic efficacy, particularly in cases where pancreatic cancer exhibits resistance to existing treatments, making GOT1 inhibition a potentially effective complementary strategy." (PMID 40733146, 2025). "Zhou reported that circ-MBOAT2 modulates tumor development and glutamine catabolism via the miR-433-3p/GOT1 axis in pancreatic cancer, suggesting circ-MBOAT2 may be a therapeutic target for pancreatic cancer." (PMID 40564276, 2025). "Importantly, inhibition of GOT1 can promote pancreatic cancer cell ferroptosis; it was found that KRAS-mutated cancer cells rely heavily on GOT1 for long-term proliferation, and GOT1 inhibition sensitizes the malignant cells to glucose deprivation." (PMID 38607041, 2024). "Experimental evidence found that pancreatic cancer cell-derived exosomes enriched with GOT1 inhibited cellular ferroptosis to promoted pancreatic cancer cell progression through mechanisms like upregulating CCR2 expression and activating the Nrf1/HO2559-1 pathway." (PMID 39777342, 2024).
pancreatic cancer (continued). "GOT1 participated in ferroptosis and inhibited pancreatic cancer cell death." (PMID 39605941, 2024). "In results 1 and 2, we confirmed that GOT1 was abnormally highly expressed in pancreatic cancer tissues and cells and that GOT1 was abundantly enriched in PANC-1 and SW1990 cell-derived exosomes, so the effects of exosomal GOT1 on tumor cells warrant further exploration." (PMID 36497150, 2022). "We found that GOT1 expression was upregulated in pancreatic cancer cell-derived exosomes." (PMID 36497150, 2022). "Furthermore, the expression of GOT1 was upregulated in pancreatic cancer cell lines AsPC1, BxPC-3, PANC-1 and SW1990 compared with normal human pancreatic ductal epithelial cell line HPDE." (PMID 36497150, 2022). "Recently, evidence has shown that GOT1 expression is upregulated in pancreatic cancer tissues and promotes cancer development, but the specific mechanism remains unclear." (PMID 36497150, 2022). "For example, GOT1 inhibition promotes pancreatic cancer cell death by ferroptosis." (PMID 35033072, 2022). "Given the binding relationship between miR-433-3p and GOT1, whether miR-433-3p regulated pancreatic cancer process by targeting GOT1 was continued to be explored." (PMID 33832516, 2021). "Thus, we further explored the relationship between miR-433-3p and GOT1 in modulating pancreatic cancer development." (PMID 33832516, 2021). "Research explained GOT1 served as a tumor promoter in pancreatic cancer growth." (PMID 33832516, 2021). "The tumorigenesis role of GOT1 has been studied in pancreatic cancer." (PMID 32266153, 2020). "Pancreatic cancer cells rely on a cytoplasmic glutaminolysis pathway producing pyruvate, which requires aspartate transaminase (GOT1, catalyzes aspartate to oxaloacetate), malate dehydrogenase (MDH1, catalyzes malate/oxaloacetate), and malate enzyme (ME1, catalyzes malate/pyruvate)." (PMID 29295482, 2017). "Likewise, in pancreatic cancer, the focus was on GOT1 in a pathway leading to NADPH production bymalic enzyme." (PMID 25749035, 2015). "Here, pyruvate, as an electron acceptor, is transported into pancreatic cancer cells via monocarboxylate transporter 1 (MCT1) and converted to lactate via lactate dehydrogenase (LDH), which can restore the redox imbalance caused by GOT2 deficiency and reverse the GOT1 pathway to synthesize Asp." (PMID 40247913, 2025). "Furthermore, miR-9-5p could directly bind to the 3’-untranslated region (3’UTR) of GOT1 and then inhibited the expression of GOT1, which stunted the proliferation, invasion, Gln metabolism, and redox homeostasis of pancreatic cancer cells." (PMID 39777342, 2024). "Additionally, GOT1 inhibition increased labile iron availability through autophagy, enhancing the activity of ferroptosis and impaired proliferation and promoted cell death of pancreatic cancer cells." (PMID 39777342, 2024). "Besides, GOT1 knockdown also could accelerate pancreatic cancer cell death by regulating iron metabolism and ferroptosis." (PMID 35978348, 2022). "All in all, we found circ-MBOAT2 silencing repressed pancreatic cancer progression via regulating cell proliferation, apoptosis, migration, invasion through repressing glutamine catabolism, and the underlying mechanism was that circ-MBOAT2 induced GOT1 expression via absorbing miR-433-3p." (PMID 33832516, 2021). "In addition, GOT1 is involved in Gln-dependent NADPH production of pancreatic cancer." (PMID 31470862, 2019). "Enzymes involved in the glutamine metabolic reprogramming (mitochondrial GLS1 (glutaminase 1), GOT1, and GOT2) are highly up-regulated in pancreatic cancer." (PMID 40247913, 2025). "As a KAT2 inhibitor, PF-04859989 inhibits GOT1 activity in a time- and pyridoxal-5 ′-phosphate (PLP)-dependent manner and selectively impairs pancreatic cancer cell line growth." (PMID 40247913, 2025). "In pancreatic cancer tissues and cells, circ-MBOAT2 and GOT1 expression were significantly upregulated, while miR-433-3p expression was downregulated." (PMID 38612727, 2024).
pancreatic cancer (continued). "Researchers remodel glutamine metabolism in pancreatic cancer by increasing the expression of aspartate aminotransferase (GOT1) and decreasing glutamate dehydrogenase (GLUD1), thereby increasing flux through GOT1-dependent pathways." (PMID 39609317, 2024). "Furthermore, mechanistic studies revealed that exosomal GOT1 suppressed pancreatic cancer cell iron death and accelerated pancreatic cancer progression by activating the Nrf2/HO-1 axis via upregulation of CCR2 expression, and our study may provide a new reference for pancreatic cancer treatment." (PMID 36497150, 2022). "This pathway in pancreatic cancer cells is primarily dominated by mutant KRAS, which results in GDH repression and GOT1 promotion." (PMID 32122374, 2020). "Further evaluations of MDH inhibitors, together with the development of specific GOT1, ME1 inhibitors are expected as therapeutic options in pancreatic cancer." (PMID 29295482, 2017). "GOT1 and GOT2 also play important roles in sustaining pancreatic cancer cell growth." (PMID 36499136, 2022). "However, in pancreatic cancer cells, GDH is repressed, but the expression of cytoplasmic aspartate transaminase (GOT1) is promoted." (PMID 32122374, 2020). "Son and his colleagues had proved that GOT1 mediates the utilization of glutamine in pancreatic cancer; oncogenic KRAS coordinates the shift from canonical type to non-canonical type of glutamine-dependent metabolism by increasing expression of GOT1 and decreasing expression of GLUD1." (PMID 25719198, 2015). "GOT1 activity could be enhanced by tumor suppressor SIRT5 deletion via facilitating GOT1’s lysine acetylation to regulate the non-canonical Gln and glutathione metabolism, and then promoted tumorigenesis of Kras-induced pancreatic cancer." (PMID 39777342, 2024). "Interestingly, in K-Ras pancreatic cancer, noncanonical Gln utilization was reported in which glutamine-derived aspartate is converted into oxaloacetate by GOT1." (PMID 35158820, 2022). "Additionally, PCSCs carrying shControl, shGLUD1, and shGOT1#2 were subjected to 2 weeks of culture with fractional IR treatment, and suppression of GOT1—but not GLUD1—significantly increased radiosensitivity in PCSCs from both pancreatic cancer cell lines." (PMID 26439804, 2015). "Overexpression of miR-9-5p inhibits the expression level of GOT1 mRNA by direct binding to its 3’UTR, thus affecting the glutamine metabolism and redox homeostasis in pancreatic cancer cells, suggesting that miR-9-5p may serve as a prognostic or therapeutic target for pancreatic cancer." (PMID 35006436, 2020).
diabetes (21 papers, 2013 to 2025). "Got1 deletion in mouse β-cells impaired β-cell function by increased glycolysis and then led to phenocopying aging and diabetes." (PMID 39777342, 2024). "Ontological classification demonstrates that these 14 genes are associated with diabetes (ALMS1P; RAET1L; GYS1; RBM47; EFR3B), cancer (RPL27A; SPAM1; PTCH1; ZNF277; USP35; CDC86), or metabolism (C3orf15; AOC2; GOT1)." (PMID 24885560, 2014).